GSDMD (gasdermin D)
Diseases named in the same sentence as GSDMD in open-access papers (continued):
Sharing a sentence is not in itself a finding about the gene and the disease.
Cerebral ischemia (continued). "Since mitochondrial dysfunction and the subsequent loss of RGC functionality and viability are the key pathological events in cerebral ischemia and glaucoma, we obtained direct evidence of GsdmD involvement in the dysfunction and death of RGCs using GsdmD−/− retinas." (PMID 37998361, 2023). "This study demonstrated that downregulated XBP-1 could inhibit pyroptosis by inhibiting the NLRP3/Caspase-1/GSDMD pathway in the hippocampus which rescues cerebral ischemia/reperfusion injury." (PMID 35497095, 2022). "Interestingly, miR-124 upregulation plays a protective role in cerebral ischemia–reperfusion injury by restricting pyroptosis as evidenced by the limited expressions of IL‐1β, IL‐18, Caspase-1, and GSDMD." (PMID 36243708, 2022). "GSDMD cleavage serves as an important checkpoint in pyroptosis in both canonical and non-canonical pathways and plays an important role in central nervous system diseases such as Alzheimer’s disease, cerebral ischemia, and multiple sclerosis." (PMID 35153737, 2021). "In addition, cleavage of GSDMD (p30) and increased LDH secretion after cerebral ischemia indicated GSDMD membrane pore formation and cellular content release." (PMID 33013286, 2020). "However, direct molecular evidence is lacking regarding how quercetin precisely regulates the NLRP3/Caspase-1/GSDMD core pyroptosis axis in microglia in cerebral ischemia models and whether it can directly target NLRP3 to inhibit this axis, thereby alleviating cerebral ischemic injury." (PMID 41892344, 2026). "In the Western blot and immunofluorescence analyses, the expression levels of pyroptosis-related factors, such as NF-κB, NLRP3, GSDMD, ASC, Caspase-1, and IL-1β, were increased significantly after cerebral ischemia-reperfusion injury." (PMID 39199474, 2024). "Double immunofluorescence staining for NeuN/Caspase1, NeuN/GSDMD, NeuN/IL-1β, MAP2/ASC, MAP2/GSDMD and NLRP1/GSDMD further confirmed that iTBS post-treatment is capable of inhibiting cerebral ischemia-induced pyroptosis of neuron in peri-infarcted area rather than at the border of infarcted core." (PMID 35690810, 2022). "Additionally, they reduce cerebral ischemia–reperfusion injury by promoting microglial polarization from M1 to M2, thereby inhibiting the expression of proteins such as NLRP3 and GSDMD." (PMID 36292924, 2022). "Notably: the beneficial effects of Nef on cerebral microvascular endothelial against brain ischemia injury was first elucidated in our study: and first revealed that promoting PGC-1α expression could inhibit BMECs pyroptosis via PGC-1α/NLRP3/GSDMD pathway." (PMID 38910141, 2024).
diabetic nephropathy (22 papers, 2019 to 2026). "In immortalized mouse podocytes, high glucose can induce podocyte pyroptosis by up-regulating NLRP3, ASC, caspase-1, and GSDMD(N), while in the kidneys of diabetic nephropathy mice, markers of pyroptosis are also significantly increased." (PMID 39850113, 2025). "Caspase-11/4 and GSDMD have been found to contribute to podocyte pyroptosis in diabetic nephropathy." (PMID 38229085, 2024). "Recent studies have found that hirudin alleviates kidney injury and blocks GSDMD-mediated pyroptosis in STZ-induced diabetic nephropathy (DN) mice and further revealed that hirudin inhibits GSDMD expression via regulating Irf2." (PMID 38067543, 2023). "MALAT1 overexpression catalyzed pyroptosis in diabetic nephropathy to accelerate kidney impairment with the involvement of increased IL‐1β, IL‐18, Caspase-1, and GSDMD." (PMID 36243708, 2022). "Targeting GSDMD has shown potential for ameliorating the inflammation of diabetic kidney disease." (PMID 39028331, 2025). "Previous studies of our research group have found that AS-IV may improve cellular pyroptosis by down-regulating the expression of GSDMD and Caspase-1 in renal tissues of diabetic nephropathy." (PMID 38820434, 2024). "Importantly, knockout of GSDMD attenuated podocyte loss in HFD/STZ-induced diabetic mice, hinting a pathophysiological role of GSDMD in the progression of diabetic nephropathy." (PMID 39253076, 2024). "The activation of the TLR4/NF-κB signaling pathway could modulate NLRP3 inflammasome activation in inflammatory bowel disease and induce GSDMD-mediated pyroptosis in tubular cells in diabetic kidney disease." (PMID 34646128, 2021). "In the context of diabetic kidney disease, studies have shown that excessive cell pyroptosis mediated by caspase-1-associated canonical cleavage of GSDMD (as well as caspase-11/4 non-canonical GSDMD cleavage) promotes podocyte damage and renal immune cell infiltration." (PMID 39920111, 2025). "However, it remains elusive whether and how GSDMD is involved in the regulation of diabetic kidney disease (DKD)." (PMID 31608008, 2019). "In diabetic nephropathy (DN) patients, DN mouse models, and in vitro high glucose (HG)-induced HK2 cell models, increased expression of pyroptosis marker proteins, cleaved-caspase-1 and GSDMD-NT, has been observed in tubular cells." (PMID 39659523, 2024).
depression (21 papers, 2021 to 2025). "The data indicated that activation of GLP-1R alleviated depression-like behaviors and associated neuroinflammation through inhibiting GSDMD-mediated microglial pyroptosis by promoting mitophagy in the depressive hippocampus." (PMID 36615696, 2022). "Furthermore, NLRP3/caspase-1/GSDMD pathway-mediated pyroptosis can cause psychiatric disorders, such as depression, complicating AA treatment." (PMID 39319843, 2025). "This work illustrates that targeting the NLRP3/Casp-1/GSDMD–mediated pyroptosis may provide potential therapeutic benefits to stress-related astrocyte loss in the pathogenesis of depression." (PMID 34877938, 2021). "Consistent with our findings, activation of the NLRP3 inflammasome was observed in AMI rats with depression, leading to the cleavage of GSDMD and subsequent release of IL‐18 and IL‐1β, thereby promoting microglial pyroptosis." (PMID 38970230, 2024). "In contrast, VX-765 inhibited only GSDMD signaling, suggesting a key role of GSDMD-dependent pyroptosis in the progression of depression." (PMID 35722622, 2022). "LPS-induced and chronic social defeat stress (CSDS) depression models have also reported the link with elevated caspase-1 and GSDMD." (PMID 36615696, 2022). "Gasdermin D (GSDMD)-mediated pyroptosis in activated microglia is involved in the pathogenesis of depression." (PMID 35496318, 2022). "Genetic KO of GSDMD, Casp-1, and astrocytic NOD-like receptor protein 3 (NLRP3) inflammasome in mice alleviated depression-like behaviors and inhibited the pyroptosis-associated protein expression." (PMID 34877938, 2021). "The astrocytic NLRP3 KO results reported here suggest that astrocytic NLRP3 inflammasome had a significant effect on the astrocytic pyroptosis via the downstream Casp-1/GSDMD pathway in the pathophysiology of depression." (PMID 34877938, 2021). "Studies have found that activation of the NLRP3/caspase-1/Gasdermin D (GSDMD) pathway leads to pyroptosis of astrocytes in the hippocampus of chronically stressed mice, enhancing neuroinflammatory responses and mediating the onset of depression." (PMID 40699781, 2025). "Interestingly, we found that the therapeutic effect of paeoniflorin was changed by blocking the expression of SIRT1, which indicated that SIRT1 and NLRP3/GSDMD played a key role in the relief of depression by paeoniflorin." (PMID 39684254, 2024). "Besides, one GSDMD+/+ mouse died on day 2 post-infection, the remaining mice showed mild clinical signs such as depression and weakness, and the death peak time of GSDMD+/+ mice was fourth to sixth days after infection." (PMID 36311722, 2022). "Given the astrocytic loss in depression and the correlation between pyroptosis and nervous system diseases, it is tempting to speculate that the NLRP3/Casp-1/GSDMD–dependent pyroptotic process contributes to the astrocytic loss in the context of depression." (PMID 34877938, 2021). "In depression, deficiency of Kir6.1 activates the NLRP3 inflammasome through excessive accumulation of mitochondrial ROS, triggering caspase-1-dependent cleavage of gasdermin D (GSDMD), leading to astrocyte pyroptosis and the release of the pro-inflammatory cytokine IL-1β." (PMID 40936908, 2025). "It has been shown that IL-1β and IL-18 released upon the activation of NLRP3 inflammatory vesicles may be key molecules in triggering the immune response in depression and further exacerbate the pathological process through Gasdermin D (GSDMD)-mediated cellular pyroptosis response." (PMID 40497971, 2025). "However, the upstream regulatory mechanisms of GSDM family members other than GSDMD remain unclear, and their relationship with depression remains to be elucidated." (PMID 35722622, 2022). "Positive and negative regulation of GSDMD via virally mediated overexpression of astrocytic GSDMD-N and genetic GSDMD KO strongly support the possibility that GSDMD could be a therapeutic target in the astrocytic pyroptosis in depression." (PMID 34877938, 2021).
depression (continued). "NLRP3-mediated gasdermin-D (GSDMD)-induced microglial pyroptosis has also been identified as a key pathway in MI and depression." (PMID 41301929, 2025). "In conclusion, we investigated the impact of SBP treatment on depressive‐like behavior in rats with depression following AMI, potentially achieved through amelioration of neuroinflammation and microglial pyroptosis mediated, at least partially, by the NLRP3/Caspase‐1/GSDMD signaling pathway." (PMID 38970230, 2024). "Up to now, all studies have concluded that the pore-formation characteristics of GSDMD-N are the driving factors of pyroptosis, given the well-known role of GSDMD-N as a downstream molecule in pyroptosis and that the mechanism of GSDMD in depression has not been studied." (PMID 34877938, 2021).
psoriasis (20 papers, 2022 to 2026). An autoimmune condition characterized by red, well-delineated plaques with silvery scales that are usually on the extensor surfaces and scalp. "By contrast, higher GSDMD expression conferred risk in psoriasis and a weaker liability in ankylosing spondylitis, yet was protective in primary sclerosing cholangitis; no instruments were found for GSDMC or GSDME." (PMID 41442179, 2026). "Taken together, these findings demonstrate that GSDMD deficiency in keratinocytes alleviates the core phenotypes of psoriasis including hyperproliferation and aberrant inflammatory response." (PMID 37673869, 2023). "We treated WT and GSDMD-deficient mice with IMQ to induce psoriasis." (PMID 39717896, 2024). "Neutrophils in psoriasis exhibit enhanced GSDMD-mediated inflammatory death, contributing to microabscess formation and fueling IL-17–driven inflammation—representing another experimentally confirmed PANoptosis-like pathway." (PMID 41440542, 2025). "In models of psoriasis, GSDMD mediates the pathogenesis of the disease, while elevated levels of GSDMD have been identified in human psoriatic lesions." (PMID 40686254, 2025). "Gasdermin D in neutrophils promotes psoriasis-like inflammation, although GSDMD reduction reduces proinflammatory cytokine release." (PMID 41440542, 2025). "GSDMD, another member of the gasdermin family, exhibits elevated expression levels in both individuals with psoriasis and in mouse models of psoriatic skin lesions." (PMID 40405066, 2025). "Immunohistochemical staining of serial sections of skin lesions from psoriasis patients and healthy control also showed that GSDMD expression is higher in psoriasis patients." (PMID 39717896, 2024). "First, we searched the GEO database and found that psoriasis patients’ neutrophils showed higher expression of GSDMD." (PMID 39717896, 2024). "Pyroptosis mediated by NLRP3/Caspase‐1/GSDMD pathway has been viewed as a participator in psoriasis." (PMID 38967379, 2024). "Serial sections of skin lesions from psoriasis patients were immunohistochemically stained with CD66b and GSDMD antibodies." (PMID 39717896, 2024). "In psoriasis, GSDMD-mediated pyroptosis was involved in the inflammatory responses in complex immune microenvironment." (PMID 38125299, 2024). "We found that GSDMD protein was activated in the skin of psoriasis, and that GSDMD in neutrophils promotes psoriasis inflammation through pyroptosis and the release of cytokines." (PMID 39717896, 2024). "It was found that the difference in lesions between the two groups was abolished after neutrophil depletion, indicating that GSDMD in neutrophil plays an important role in the pathogenesis of IMQ-induced psoriasis-like lesions in mice." (PMID 39717896, 2024). "In this study, we dissected the role of GSDMD protein, a key pyroptosis executioner, in the context of psoriasis." (PMID 39717896, 2024). "In our earlier experiment, which has been published, we also studied the role of GSDMD in psoriasis and found it overexpressed in psoriatic plaque compared to healthy skin and suggested its role in psoriasis which seems convergent with what we observed now." (PMID 38693919, 2024). "Immunohistochemical staining of serial sections of skin lesions from psoriasis patients and healthy control also showed that GSDMD expression is higher in psoriasis lesion, especially in neutrophils." (PMID 39717896, 2024). "Both studies underscore the significant role of GSDMD-mediated pyroptotic signaling in psoriasis, and the consistent involvement of KC cells and neutrophils further emphasizes the potential therapeutic value of targeting GSDMD signaling in psoriasis treatment." (PMID 39717896, 2024). "To further investigate neutrophilic pyroptosis in psoriasis, we detected the expression of GSDMD and its N-terminal fragments by WB in the psoriatic skin of WT mice, Gsdmd-/- mice, and cKO mice." (PMID 39717896, 2024).
psoriasis (continued). "Knockout of GSDMD in vivo is effective in significantly ameliorating IMQ-induced psoriasis-like lesions and reducing the level of skin inflammation, which also notably reduces the expression of the pyroptosis-inducing inflammatory cytokine IL-1β." (PMID 39717896, 2024). "Nevertheless, combining previous studies and our findings, we can believe that GSDMD-mediated pyroptosis, which is a dynamic biological process, particularly neutrophil pyroptosis, is involved in the inflammation of psoriasis, especially in the early stage." (PMID 39717896, 2024). "To explore the role of GSDMD in pathogenesis of psoriasis, we compared difference of phenotype between Gsdmd−/− mice and WT mice after imiquimod stimulation." (PMID 37673869, 2023). "We found that N-terminal GSDMD (N-GSDMD) was aberrantly expressed in epidermis of skin lesion in psoriasis patients and imiquimod-induced psoriasis-like dermatitis (IIPLD) mice." (PMID 37673869, 2023). "In summary, we discover that GSDMD-mediated keratinocyte pyroptosis contributes to pathogenesis of psoriasis." (PMID 37673869, 2023). "Taken together, these findings indicate that targeting GSDMD-mediated pyroptosis can be considered as a potential therapeutic strategy in treatment of psoriasis." (PMID 37673869, 2023). "Taking into account the documented role of GSDMD in cell death, proliferation, and differentiation, we became interested in the investigation of this protein in the context of psoriasis pathogenesis and potential clinical application in this dermatosis." (PMID 37685853, 2023). "Hereby, we present our results regarding the possible role of GSDMD in psoriasis pathogenesis, with reference to its clinical application." (PMID 37685853, 2023). "GSDMD has been documented to participate in this process and it has also been discovered that NETosis plays a role in psoriasis." (PMID 37685853, 2023). "Whereas most research focused on one or two PRGs in vivo or vitro, for instance, the pathogenesis of psoriasis is closely related to caspase-1, IL-1β, IL-18, or GSDMD." (PMID 36110207, 2022). "The newly identified role of disulfiram in GSDMD inhibition, combined with these novel delivery techniques, suggests promising therapeutic applications for this established drug in the management of psoriasis." (PMID 40332377, 2025). "We found that after psoriasis induction, the GSDMD N-terminus was only weakly expressed in the skin of cKO mice, whereas it was strongly expressed in WT mice, suggesting that GSDMD-mediated neutrophil pyroptosis is one of the important components of cell pyroptosis in psoriasis." (PMID 39717896, 2024). "Our study is for the first time demonstrating that GSDMD-mediated neutrophil pyroptosis in psoriasis is involved in psoriatic inflammation and may affect the inflammatory network in psoriasis." (PMID 39717896, 2024). "GSDMD depletion in neutrophils attenuates the development of skin inflammation in psoriasis." (PMID 39717896, 2024). "Therefore, our study aimed to investigate the role of GSDMD-mediated immune cell pyroptosis in psoriasis." (PMID 39717896, 2024). "Our recent investigation revealed a correlation between GSDMD-mediated pyroptosis and hyperproliferation and aberrant differentiation of keratinocytes in psoriasis, and targeting GSDMD could alleviate the severity of psoriasis-form dermatitis." (PMID 38429278, 2024). "Results showed that the expression of the GSDMD protein (dark brown staining) was upregulated in AD lesions and psoriasis lesions, and there were more positive cells (in red circles) in the psoriasis epidermis (38%) than in AD epidermis (19.68%) and HC epidermis (3.6%)." (PMID 38250727, 2024). "While previous studies have showed that the expression of GSDMD is increased in lesions of patients with psoriasis, and the pyroptosis of keratinocytes plays a role in inflammation seen in psoriasis." (PMID 39717896, 2024).